ATF6 (activating transcription factor 6)
Diseases named in the same sentence as ATF6 in open-access papers (continued):
Sharing a sentence is not in itself a finding about the gene and the disease.
Hepatic steatosis (41 papers, 2012 to 2025). Steatosis is a term used to denote lipid accumulation within hepatocytes. "Overexpression of a repressive version of ATF6 (dnATF6) elevates the susceptibility to hepatic steatosis in mice that manifest insulin resistance due to a high-fat diet." (PMID 38025713, 2023). "The phenotypic outcome of the ER stress insult in ATF6α-knockout mice was hepatic steatosis caused by induction of lipid droplet formation due to reduced β-oxidation of FA and attenuated VLDL formation." (PMID 22195283, 2012). "Elevated ATF6 expression in the liver fosters hepatic fatty acids oxidation, providing protection for mice with insulin resistance caused by a high-fat diet from the impact of hepatic steatosis." (PMID 38025713, 2023). "Additional evidence of the functionality of 147 in the liver was evident in its ability to reduce hepatic triglycerides, which are a hallmark of hepatic steatosis, demonstrating improved ER proteostasis in the liver (blue); this beneficial effect of 147 was also lost upon deletion of ATF6 (black)." (PMID 30643122, 2019). "However, under ER stress conditions, ATF6α knockout mice exhibited severe liver injury and hepatic steatosis caused by inhibition of fatty acid β-oxidation and VLDL formation." (PMID 24847353, 2014). "In response to endoplasmic reticulum stress, activating transcription factor 6α (ATF6α) can attenuate liver steatosis by stimulating PPARα-mediated FAO." (PMID 39911797, 2025). "The effect and mechanism of the ATF6‐mediated UPR following surgical stress on the course of liver fatty diseases and hepatocarcinogenesis are worthy of further investigation." (PMID 40801087, 2025). "WS/WD developed very quickly in these salmon (within a week), and given this timeframe, it is difficult to determine the role of ATF6 in this particular model of hepatic steatosis/steatohepatitis." (PMID 39056688, 2024). "Mice with genetic deletions of either ER stress-sensing pathways (ATF6α, eIF2α, IRE1α) or quality control (Dnajc3) show a similar response to ER stress, including the development of hepatic steatosis." (PMID 38279270, 2024). "When exposed to tunicamycin, ATF6α-deficient mice exhibit persistent express CHOP, inhibition of C/EBPα (CCAAT/enhancer-binding protein α), and develop hepatic steatosis." (PMID 38025713, 2023). "In the present study, we demonstrated that H2S level was significantly downregulated in hepatic-specific ATF6 knockout mice, leading to hepatic steatosis and glucose tolerance." (PMID 38007457, 2023). "ATF6 attenuate hepatic steatosis by increasing fatty acid oxidation through peroxisome proliferator-activated receptor α (PPAR α)." (PMID 38007457, 2023). "Continued on the previous study, we identified that ATF6 ameliorates liver steatosis and inflammation by upregulating CBS expression and H2S synthesis via SIRT1 sulfhydration." (PMID 38007457, 2023). "In order to clarify the mechanism by which ATF6 regulates H2S synthesis to ameliorate liver steatosis and inflammatory environment, we conducted the present study." (PMID 38007457, 2023). "Mice with ATF6α gene knockout exhibit significant liver dysfunction and fatty liver, and a notable accumulation of neutral (e.g., triglycerides and cholesterol) in liver." (PMID 38025713, 2023). "Definitely, the UPR is activated via inositol-requiring enzyme 1 (IRE1), PKR-like ER kinase (PERK) and activating transcription factor 6 (ATF6) in the regulation of hepatic steatosis and the cellular response to lipotoxic stress." (PMID 35739990, 2022). "Deficiency in ATF6 prevents steatosis during chronic ER stress, but exacerbates it during acute ER stress, suggesting that ATF6 plays both a protective and a pathological role in fatty liver." (PMID 35958574, 2022). "Resveratrol improves hepatic steatosis by mediating the Sirt1/activating transcription factor 6 dependent mechanism." (PMID 34684653, 2021).
Hepatic steatosis (continued). "Hepatic ATF6 knockdown or overexpression of its dominant-negative form by adenovirus in WD-fed mice exacerbates insulin resistance and hepatic steatosis with reduced transcriptional activity of the PPARα/RXR complex." (PMID 32660130, 2020). "Conversely, overexpression of the cleaved active from of ATF6 protects mice from hepatic steatosis and promotes hepatic FA oxidation." (PMID 32660130, 2020). "In zebrafish, Atf6 has been investigated in fatty liver disease and steatosis, but how Atf6 is involved in other tissue types or disease processes has not been investigated." (PMID 31852729, 2020). "It has been previously demonstrated that naltrexone down-regulated GRP78 and ATF6 gene expression, alleviated ER stress, and improved liver steatosis in mice." (PMID 32373294, 2019). "During the response to ER stress, all three main brunches of UPR including PERK, IRE1, and ATF6 pathways are activated and mediates hepatic steatosis." (PMID 31632274, 2019). "In a zebrafish model of fatty liver disease, ATF6 prevents hepatic steatosis following tunicamycin-induced acute ER stress whereas ATF6 potentiates steatosis due to chronic ER stress." (PMID 29801500, 2018). "Under ER stress conditions, ATF6α knockout mice exhibited hepatic steatosis due to the inhibition of fatty acid β-oxidation, and was accompanied by reduced expression of the related genes, including PPARα, CPT1, CPT2 and ACOX1." (PMID 30081561, 2018). "Previous studies showed that liver-specific IRE1α deletion and ATF6 knockout mice developed serious hepatic steatosis upon pharmacological ER stress." (PMID 26805874, 2016). "This study suggest that ATF6 can play both protective and pathological roles in fatty liver disease." (PMID 24847353, 2014). "Previously, it was reported that Atf6 protects against hepatic steatosis and contributes to the overall maintenance of homeostasis in the ER during stress." (PMID 23894352, 2013). "Overexpression of the ER stress chaperone BIP (GRP78) in ob/ob mice (as with Ildr2) reverses hepatic steatosis, and hypomorphic expression of UPR modulators Atf6, Ire1α, Chop, and Crebh in mouse models cause hepatic dyslipidemia." (PMID 23826244, 2013). "Several recent studies have examined the role of ATF6 in vivo by studying the role of ER stress on fatty liver disease and lipid droplet formation in ATF6α-knockout mice." (PMID 22195283, 2012). "Conversely, the overexpression of active nuclear ATF6 promotes lipogenesis and hepatic steatosis in alcohol-treated zebrafish, even though the majority of evidence indicates that ATF6 suppresses lipid synthesis and alleviates hepatic steatosis." (PMID 41465302, 2025). "Therefore, PERK and ATF6 pathways have emerged as particularly promising therapeutic targets for the prevention of fatty liver disease." (PMID 38216941, 2024). "ATF6 may attenuate HFD-induced fatty liver and hepatic steatosis, and it has been verified that liver specific knockout of ATF6 exacerbated HFD-induced hepatic steatosis and glucose intolerance leading to liver metabolic damage." (PMID 38007457, 2023). "In addition, the mechanism by which ATF6 regulates H2S synthesis to ameliorate liver steatosis, and the role of CBS and inflammatory factors in liver metabolism remains uncertain." (PMID 38007457, 2023). "Liver histology analysis suggested that ATF6−/− mice showed liver steatosis fed with HFD." (PMID 38007457, 2023). "However, the deep molecular mechanism by which ATF6 attenuates hepatic steatosis and glucose homeostasis need further investigation in the future." (PMID 38007457, 2023). "It has been reported that ATF6 is important for attenuating hepatic steatosis under ER stress triggers, such as HFD, and that hepatic ATF6-conditional knockout causes lipid accumulation in the liver through the upregulation of the PPARγ pathway that facilitates lipogenesis." (PMID 37172729, 2023).
Hepatic steatosis (continued). "First, in this study, we demonstrated that GYY4137, the H2S releasing agent, ameliorated the glucose intolerance and lipid metabolism abnormalities on ATF6−/− mice fed with HFD, suggesting that ATF6 attenuates hepatic steatosis in fatty liver by inducing H2S accumulation." (PMID 38007457, 2023). "On the one hand, ATF6 protects β cells from ER stress, inhibits hepatic steatosis, and reduces hyperglycemia and hyperinsulinemia in obese mice with hepatic overexpression; on the other hand, ATF6 is also involved in the development of hyperlipidemia and insulin resistance." (PMID 35958574, 2022). "Direct enhancement of ER stress induced with chemical agents and genetic mutations of ER stress molecules (including PERK/eIF2α, IRE1/ X-box binding protein 1 (XBP1) and ATF6) stimulate hepatic steatosis via controlling lipid synthesis and the inflammatory response." (PMID 32521713, 2020). "Recent study has pointed out that ATF6α-knockout mice show enhanced hepatic steatosis caused by impaired formation of VLDL due to destabilized apoB100, whereas the exact mechanism of ATF6 in regulating apoB100 formation still remains unclear." (PMID 31632274, 2019). "Therefore, ATF6 could be a novel therapeutic strategy for high-fat diet induced fatty liver metabolic abnormalities." (PMID 38007457, 2023). "The results suggested that HQT has protective effect against hepatic steatosis and inflammation in NAFLD rats by attenuating ER stress, and the potential mechanism is through inhibition of PERK and ATF6 pathways." (PMID 38216941, 2024). "Second, our results indicated that ATF6 promote SIRT1 signal and regulate the inflammatory response in liver steatosis." (PMID 38007457, 2023). "ATF6α-knockout mice showed lower fatty acid β-oxidation, attenuated very-low-density lipoprotein (VLDL) formation and increased hepatic steatosis in response to an ER stress inducer." (PMID 33849585, 2021). "In parallel with IRE1α, ATF6 and PERK activation, adult male IUGR animals show an impairment of glucose tolerance and the development of hepatic steatosis with progression to fibrosis." (PMID 29897997, 2018). "BPA exacerbated hepatic steatosis in the OVX HBPA group, elevating lipid/collagen deposition with reduced Mttp mRNA and upregulated β-oxidation (Acox1, Acadvl), mitochondrial uncoupling (Ucp2), ER stress (Hyou1, Atf6), and liver injury (Tgfb1, Casp8) genes." (PMID 40475995, 2025). "Moreover, ER stress activates the activating transcription factor 6 (ATF6) pathway to upregulate nuclear factor-kappa B (NF-κB) expression, exacerbating the hepatic inflammatory response and leading to liver steatosis to non-alcoholic steatohepatitis (NASH)." (PMID 38216941, 2024). "The absence of the ATF6α leads to blocked fatty acid oxidation, further promoting the early development of fatty liver." (PMID 38025713, 2023). "Depletion of ATF6α promotes ER stress response, aggravated liver dysfunction, reduced fatty acid oxidation and very low-density lipoprotein (VLDL) formation, resulting in hepatic lipid accumulation and liver steatosis in mice." (PMID 30081561, 2018). "It is known that high levels of ATF6 activation induce hepatic steatosis in zebrafish, whereas lower levels do not." (PMID 27435961, 2016). "At the same time, immunoblot analysis of the PERK, IRE1α, ATF6, and SREBP pathways reveals no significant role for these UPR pathways in the etiology of hepatic steatosis associated with early-stage ALD." (PMID 22829816, 2012). "Mechanistically, RSV could ameliorate NAFLD and hepatic steatosis in obese mice by promoting the SIRT1/AMPK pathway, possibly mediated by activating SIRT11 as a Sirt1 enhancer, and ameliorating the accumulation of LDs by mediating a SIRT1/ATF6-dependent mechanism." (PMID 35431994, 2022). "However, we did not detect any significant changes in ATF6, p-PERK, p-IRE1, p-eIF2α., or XBP1 splicing, after one week of HFat feeding when hepatic steatosis and insulin resistance were clearly present." (PMID 22355328, 2012).
breast cancer (31 papers, 2012 to 2026). A primary or metastatic malignant neoplasm involving the breast. "The ectopic expression of ATF6α alone was sufficient to cause cellular senescence in MCF-7 human breast cancer cells as well as Caki-1 human renal cancer cells." (PMID 39466820, 2024). "COSMIC analysis of breast cancers revealed just ten unique exonic ATF6 mutations in over two-thousand breast tumour samples (0.47%)." (PMID 30248920, 2018). "Clinical analyses reveal that TP63 and FOXO3a expression are significantly reduced in breast cancer tissues compared to normal tissues, whereas ATF6 and GRP78 expression are elevated." (PMID 40223122, 2025). "In this study, we demonstrate that ER stress-activated ATF6α promotes breast cancer cell migration and metastasis by downregulating the expression of ΔNp63α, a key metastasis suppressor." (PMID 40223122, 2025). "In contrast, the expression of ATF6 or GRP78 was significantly elevated in breast cancer tissues compared to normal tissues." (PMID 40223122, 2025). "Our previous findings demonstrated that hypoxia-induced ER stress downregulates ΔNp63α via the ATF6α pathway, facilitating metastatic spread, particularly in breast cancer models." (PMID 40223122, 2025). "In our previous work, we found that hypoxia-induced ER stress promotes breast cancer metastasis by downregulating ΔNp63α through two key signaling pathways: IRE1α-XBP1s and ATF6α." (PMID 40223122, 2025). "In this study, we provide evidence that ATF6α suppresses ΔNp63α through the GRP78-AKT1-FOXO3a axis to facilitate breast cancer metastasis." (PMID 40223122, 2025). "In this study, our goal is to comprehend the early-stage molecular mechanism of cellular senescence induced or mediated by the ER stress-ATF6α pathway in the MCF-7 breast cancer cell line." (PMID 39466820, 2024). "We have shown here that a decrease in the OCT-1 concentration in breast cancer cells makes the ATF6 adaptive pathway less efficient thereby attenuating the adaptive response of cancer cells to EPR stress and promoting decompensated EPR stress and cell death." (PMID 36143471, 2022). "Studies have elucidated that hsa-miR-103 and hsa-miR-107 were involved in Wnt3a/β-catenin/ATF6 signaling pathway and were critical to the progression of colorectal cancer, Alzheimer's disease, breast cancer and cardiac function 33-36." (PMID 34093822, 2021). "We next explored how these genes interact in breast cancer cells by constructing wild-type and mutated pmiGLO/ATF6-3′-UTR and pmiGLO/ATF6-3′-UTR plasmids and performed luciferase reporter assays." (PMID 32376943, 2020). "The experimental data suggested that ER stress biomarkers including GRP78, PERK, ATF6, IRE1α and PD‐L1 were overexpressed in breast cancer tissues relative to paracancerous tissues." (PMID 32672418, 2020). "Higher expression of GRP78, PERK, ATF6 and IRE1α24 has been noted in breast cancer tissues, indicative of stimulation of ER stress in breast cancer cells." (PMID 32672418, 2020). "Meanwhile, enhanced IRE1 activity has been demonstrated to increase the production of protumorigenic cytokines in breast cancer cells to survive paclitaxel, and ATF6 is required to promote mTOR activation and STAT3 signaling to gain chemoresistance." (PMID 33396303, 2020). "ER chaperone BIP and ER sensors (PERK, IRE1A, and ATF6) were upregulated in NMT1 knockdown breast cancer cell lines, suggesting shRNA mediated NMT1 knockdown actually cause ER stress." (PMID 30446635, 2018). "And we individually established PERK, IRE1A, and ATF6 knockdown cell lines in NMT1 knockdown breast cancer cells." (PMID 30446635, 2018). "Taken above all results, it suggests that AMP induces expression of CHOP through PERK and ATF6-mediated signaling pathway in human breast cancer cells, and PERK-CHOP pathway is mainly involved in ER stress-mediated cell apoptosis induced by AMP." (PMID 24551210, 2014).
breast cancer (continued). "Moreover, low TP63 expression (p = 0.0012), high ATF6 expression (p = 0.0055) and high GRP78 expression (p = 0.0014) were significantly associated with poor prognosis in breast cancer patients." (PMID 40223122, 2025). "These protein levels can be restored in RHBDF1-deficient breast cancer cells by artificial overexpression of RHBDF1 but not IRE1 or ATF6." (PMID 39420837, 2024). "Yu et al4 showed that silencing ATF6α inhibits EGF‐induced breast cancer cell proliferation." (PMID 30414263, 2018). "Experimental evidence suggesting a direct role for ATF6 in breast cancer is limited." (PMID 30248920, 2018). "However, ATF6 knockdown was reported to reduce angiogenesis and tumour volume in a breast cancer xenograft model and to significantly decrease estrogen-induced growth." (PMID 30248920, 2018). "Specifically, we demonstrated that (i) AMP induced the up-regulation of GRP78, p-PERK, p-elF2α, and cleaved ATF6α, all of which mediate ER stress in both breast cancer cells; (ii) AMP also increased the expression of CHOP, which is an important apoptotic inducer." (PMID 24551210, 2014). "To determine whether the ATF6 fragment generated during EV71 infection in cells was caused by caspase activation, we infected MCF7 human breast cancer cells, which are deficient in caspase-3 protein levels and activity, in the presence or absence of caspase inhibitors." (PMID 29386036, 2018). "Tramadol differentially affected three primary UPR pathways – IRE1, ATF6, and PERK – in MDA-MB-231 and MCF-7 breast cancer cells." (PMID 41526224, 2026). "To compare the expression levels of ΔNp63α, ATF6α, GRP78, and FOXO3a in breast cancer tissue versus normal tissue, we analyzed publicly available datasets." (PMID 40223122, 2025). "The first finding of this study was that ER stress was activated in breast cancer tissues, as evident by increased expression of GRP78, PERK, ATF6 and IRE1α in tumour tissues." (PMID 32672418, 2020). "The general trend of the three HER2/neu-positive breast cancer cell lines tested was that they possessed higher basal levels of DDIT3/CHOP, ATF6 and spliced XBP1 and that these levels increased in response to palmitate treatment." (PMID 27464732, 2016). "Data revealed that AMP exposure time-dependently increased the expression of GRP78, p-PERK, p-elF2α, cleaved ATF6α, and CHOP in both breast cancer cell lines MCF-7 and MDA-MB-231." (PMID 24551210, 2014). "Additionally, the activation of transcription factor 6 (ATF6) following ER stress inhibits the expression of ΔNp63α through the GRP78-AKT1-FOXO3a signaling pathway, thereby promoting breast cancer metastasis." (PMID 40519935, 2025). "In mechanistic studies, coculture of breast cancer cell derived ExVs with macrophages suggested that endoplasmic reticulum stress biomarkers including GRP78, PERK, ATF6, IRE1α and PD-L1 were overexpressed in breast cancer tissues relative to para-cancerous tissues." (PMID 33435564, 2021). "Moreover, knockdown of ATF6 expression effectively reduced the levels of ATF6 mRNA and protein as well as the level of AFAP1-AS1 in breast cancer cells." (PMID 32376943, 2020). "A detailed analysis in our SUM159 breast cancer cell system of key proteins involved in the 3 different UPR branches showed decreased expression of the chaperone Grp78 and the transcriptions factors ATF4, ATF6, sXBP1, and CHOP." (PMID 29295867, 2018). "In an invasive breast cancer cell line, GRB2 was found to regulate GTPases activation, and may also trigger ATF4 and ATF6." (PMID 28767067, 2017). "The abundance of the ATF6 full-length isoform declined in the presence of DTT, which activates each branch of the UPR, but was unchanged between the MAL3-101 sensitive (MCF7 and MDA MB 231) and resistant (MDA MB 453 and MDA MB 361) breast cancer cells after MAL3-101 treatment." (PMID 34180400, 2021).